OR5F1 (olfactory receptor family 5 subfamily F member 1)
Description:
Odorant receptor.
Synonyms: OR11-10
Tractability: Antibody: UniProt places it where antibodies can reach, with medium confidence; UniProt predicts a signal peptide or a membrane-spanning region; its Gene Ontology location is reachable by antibodies, with medium confidence. PROTAC: ubiquitination databases record sites on it.
Gene: Protein-coding gene on chromosome 11 (55,993,681 to 55,994,625, reverse strand). Ensembl gene ENSG00000149133.
Subcellular location: Cell membrane
Pathways (Reactome):
Sensory Perception: Expression and translocation of olfactory receptors
Gene Ontology:
Molecular function: odorant binding; olfactory receptor activity; G protein-coupled receptor activity
Biological process: sensory perception of smell; detection of chemical stimulus involved in sensory perception of smell; G protein-coupled receptor signaling pathway
Cellular component: membrane; plasma membrane
Genetic constraint (gnomAD): Missense variants: 401 observed, 345.27 expected, observed/expected ratio (o/e) 1.16, 90% interval 1.07 to 1.26. Synonymous variants: 169 observed, 143.75 expected, observed/expected ratio (o/e) 1.18, 90% interval 1.04 to 1.34.
Homologues: Orthologues: chimpanzee OR5F1 (96% identical), macaque OR5F1 (93% identical), dog OR5F1 (83% identical), mouse Or5be3 (44% identical), rat Or5be3 (44% identical), mouse Or13a23 (22% identical). Paralogues in human: OR5B21 (53% identical), OR8H1 (52% identical), OR5AP2 (52% identical), OR5AR1 (52% identical), OR8I2 (52% identical), OR5AN1 (51% identical), OR8H2 (51% identical), OR5B12 (51% identical), OR5C1 (51% identical), OR5M11 (51% identical), OR8D1 (51% identical), OR8H3 (51% identical), and 84 more.
Diseases named in the same sentence as OR5F1 in open-access papers:
OR5F1 is named in the same sentence as 1 disease in open-access papers, as found by Europe PMC text mining. Sharing a sentence is not in itself a finding about the gene and the disease. The quoted sentences say what the papers report.
malignant peritoneal mesothelioma (1 paper, 2025). An aggressive malignant mesothelioma that arises from the peritoneum. "Recently, pediatric malignant peritoneal mesothelioma cases have been genetically studied, with alterations observed in ALK, EWSR1, FUS1, YY1, or in AURKA, AURKC, HLA-1B, ZNF-217, OR5F1, and MEN1 genes, but not in BAP1." (PMID 40725095, 2025).